NSUN5P1 (NSUN5 pseudogene 1)
Synonyms: WBSCR20B; formerly NSUN5B
Gene: Transcribed unprocessed pseudogene on chromosome 7 (75,410,368 to 75,416,597, forward strand). Ensembl gene ENSG00000223705.
Diseases named in the same sentence as NSUN5P1 in open-access papers:
NSUN5P1 is named in the same sentence as 4 diseases in open-access papers, as found by Europe PMC text mining. Sharing a sentence is not in itself a finding about the gene and the disease. The quoted sentences say what the papers report.
cervical cancer (1 paper, 2021). A primary or metastatic malignant neoplasm involving the cervix. "The role of C6orf223 and NSUN5P1 in cancer has not yet been reported, but many studies have shown that SNHG4 is involved in multiple cancers, including osteosarcoma, prostate cancer, and cervical cancer." (PMID 33744866, 2021).
NSUN5P1 also shares sentences with these, for which no sentence is quoted: cancer (1 paper); osteosarcoma (1); prostate carcinoma (1).